CCND2 (cyclin D2)
Description:
Regulatory component of the cyclin D2-CDK4 (DC) complex that phosphorylates and inhibits members of the retinoblastoma (RB) protein family including RB1 and regulates the cell-cycle during G(1)/S transition. Phosphorylation of RB1 allows dissociation of the transcription factor E2F from the RB/E2F complex and the subsequent transcription of E2F target genes which are responsible for the progression through the G(1) phase. Hypophosphorylates RB1 in early G(1) phase. Cyclin D-CDK4 complexes are major integrators of various mitogenenic and antimitogenic signals.
Synonyms: KIAK0002; MPPH3
Tractability: Small molecule: a high-quality ligand is known; it belongs to a druggable protein family. PROTAC: UniProt records ubiquitination sites on it; ubiquitination databases record sites on it.
Gene: Protein-coding gene on chromosome 12 (4,269,771 to 4,306,933, forward strand). Ensembl gene ENSG00000118971.
Subcellular location: Nucleus; Cytoplasm; Nucleus membrane; Cytoplasm (Isoform 2)
Subcellular location (Human Protein Atlas): Nucleoplasm
Pathways (Reactome):
Cell Cycle: Cyclin D associated events in G1; Drug-mediated inhibition of CDK4/CDK6 activity
Disease: Defective binding of RB1 mutants to E2F1,(E2F2, E2F3)
Gene expression (Transcription): Regulation of RUNX1 Expression and Activity
Gene Ontology:
Molecular function: cyclin-dependent protein serine/threonine kinase activator activity; protein binding; protein kinase binding; protein serine/threonine kinase activator activity; cyclin-dependent protein serine/threonine kinase regulator activity
Biological process: G1/S transition of mitotic cell cycle; negative regulation of apoptotic process; positive regulation of cell population proliferation; positive regulation of G1/S transition of mitotic cell cycle; positive regulation of mitotic cell cycle phase transition; regulation of G1/S transition of mitotic cell cycle
Cellular component: chromatin; cyclin D2-CDK4 complex; cyclin-dependent protein kinase holoenzyme complex; cytoplasm; cytosol; nuclear membrane; nucleolus; nucleoplasm; nucleus; microtubule organizing center
Genetic constraint (gnomAD): Loss-of-function variants: 6 observed, 30.76 expected, observed/expected ratio (o/e) 0.2, 90% interval 0.11 to 0.38. The upper end of that interval is the gene's LOEUF score, 0.38, which puts it in group 1 of 6, group 1 being the genes least tolerant of losing a copy. Missense variants: 235 observed, 391.09 expected, observed/expected ratio (o/e) 0.6, 90% interval 0.54 to 0.67. Synonymous variants: 150 observed, 161.53 expected, observed/expected ratio (o/e) 0.93, 90% interval 0.81 to 1.06.
Gene-disease validity (ClinGen):
ClinGen rates the evidence that CCND2 causes each of these diseases.
megalencephaly-polymicrogyria-polydactyly-hydrocephalus syndrome 3 (autosomal dominant): Definitive. Any megalencephaly-polymicrogyria-postaxial polydactyly-hydrocephalus syndrome in which the cause of the disease is a mutation in the CCND2 gene.
Cancer hallmarks: proliferative signalling (promotes)
Homologues: Orthologues: chimpanzee CCND2 (100% identical), guinea pig CCND2 (97% identical), rabbit CCND2 (97% identical), dog CCND2 (95% identical), pig CCND2 (94% identical), rat Ccnd2 (93% identical), mouse Ccnd2 (92% identical), tropical clawed frog tigar (84% identical), zebrafish ccnd2a (81% identical), zebrafish ccnd2b (69% identical), Drosophila melanogaster CycD (41% identical), Caenorhabditis elegans cyd-1 (27% identical), and 6 more. Paralogues in human: CCND1 (63% identical), CCND3 (62% identical), CCNA1 (27% identical), CCNA2 (26% identical), CCNB2 (23% identical), CCNJ (23% identical), CCNB1 (22% identical), CCNE1 (22% identical), CCNE2 (22% identical), CCNF (21% identical), CCNO (21% identical), CCNJL (20% identical), and 6 more.
Diseases named in the same sentence as CCND2 in open-access papers:
CCND2 is named in the same sentence as 220 diseases in open-access papers, as found by Europe PMC text mining. Sharing a sentence is not in itself a finding about the gene and the disease. The quoted sentences say what the papers report.
breast carcinoma (103 papers, 2003 to 2025). "It has been reported that hypermethylation of the CCND2 promoter can be detected in the early stages of breast cancer and is associated with its expression silencing." (PMID 40678058, 2025). "CCND2-promoter hypermethylation was found at an early stage of breast cancer tumorigenesis and was associated with the silencing of CCND2 expression." (PMID 37510349, 2023). "Although there are few reports on the functions of the PHF7 and CCND2 in breast cancer, they are associated with cardiac disease, bladder squamous cell carcinoma, and neuroblastoma." (PMID 37426199, 2023). "Aberrant methylation in the CCND2 promoter was also associated with a poor prognosis in breast cancer and lung cancer using the log-rank test (p = 0.045 and p = 0.022, respectively)." (PMID 30308939, 2018). "Aberrant methylation in the CCND2 promoter was also associated with a poor prognosis in lung cancer and breast cancer using multivariate Cox proportional hazard model analysis (p = 0.039 and p = 0.009)." (PMID 30308939, 2018). "Promoter hypermethylation of CCND2 and low CCND2 expression were also associated with a poor prognosis in overall lung and breast cancer, likely because most lung and breast cancer patients with a poor survival have lung adenocarcinoma and TNBC, respectively." (PMID 30308939, 2018). "This isoflavone mix induced increased dose related methylation in the proliferation regulatory genes associated with breast cancer development, retinoic acid receptor β2 (RARβ2) and cyclin D2 (CCND2)." (PMID 25647662, 2015). "The increased expression of Ccdn2 is discordant with enhanced tumorigenesis of HFD-E tumors, as loss of cyclin D2 expression is frequent in breast cancers." (PMID 24156623, 2013). "Recently, a study involving a large cohort of breast cancer patients (n = 388) showed that high LOH frequencies were associated with the aggressiveness of breast cancer, and in particular, the observed CCND2 loss was a strong indicator of an unfavorable prognosis." (PMID 27056366, 2016). "The methylation of CCND2 promoter was also detected in ductal carcinoma in situ, which suggested that loss of CCND2 is an early event in tumorigenesis and may associated with the evolution of breast cancer." (PMID 27583477, 2016). "Genome‐wide methylation and QMSP have shown that CCND2 promoter hypermethylation was detected in 40.9% of breast tumors and 44.4% of plasma circulating cfDNA of patients, and could serve as a potential diagnostic and prognostic marker in breast cancer." (PMID 33942482, 2021). "MiR-206 conjugated gold nanoparticle-based, targets therapy in breast cancer cells by blocking the G1/S transition by targeting cyclin D2 (CCND2)." (PMID 40061926, 2025). "Using demethylating agents can increase CCND2 expression in breast cancer samples and inhibit cancer cell growth by inducing cell cycle arrest." (PMID 40678058, 2025). "Kaplan-Meier curves show that SDC1, NACAD, ZMAT3, CCND2, XG and SGCE are associated with prognosis in breast cancer patients." (PMID 39664194, 2024). "G1/S-specific cyclin-D2 (CCND2) was associated with cell proliferation and apoptosis in breast cancer." (PMID 38259849, 2023). "Administering the de-methylating agent antroquinonol D increased CCND2 expression in breast cancer samples and resulted in reduced cancer cell growth through cell cycle arrest." (PMID 37510349, 2023). "let-7a-5p enhanced radiation-induced tumor repression by inhibiting the self-renewal function of breast cancer stem cells, and its radiation targets CCND2, TSPYL5, and BCL2L1 were identified." (PMID 37569824, 2023). "Previous studies have shown that CCND2 is aberrantly expressed in a variety of tumor tissues, such as lung cancer, breast cancer, and gastric cancer." (PMID 35266852, 2022). "In breast cancer cells, only three genes, including cyclin D2, were abnormally hypermethylated, and ATO led to their demethylation." (PMID 36619302, 2022).
breast carcinoma (continued). "CCND2 promoter methylation was previously reported to be a common event in breast cancer and have prognostic value." (PMID 33461604, 2021). "While the role of CCND2 is still controversial in a different type of tumors, high-level expression of CCND2 was observed in testicular and ovarian tumors, and aberrant promoter methylation status of CCND2 was shown in breast cancer tissues." (PMID 31921385, 2019). "Aberrant methylation and other mechanisms that mediate CCND2 low expression can be induced by antroquinonol D in breast cancer and lung cancer cells." (PMID 30308939, 2018). "Promoter hypermethylation of CCND2 and low CCND2 expression were associated with a poor prognosis, especially in NSCLC and breast cancer patients." (PMID 30308939, 2018). "Genome-wide methylation and quantitative methylation-specific real-time polymerase chain reaction (PCR) showed CCND2 promoter hypermethylation in Taiwanese breast cancer patients." (PMID 30308939, 2018). "Further analysis of the methylation patterns of other cancer types revealed that the CCND2 promoter hypermethylation was significant in breast cancer, lung adenocarcinoma, and liver cancer, but not in esophageal and colon cancers." (PMID 30308939, 2018). "An increase in the methylation level of the CCND2 promoter CpG site cg22678952 when compared with paired adjacent normal tissues was found in Taiwanese breast cancer patients." (PMID 30308939, 2018). "In conclusion, alterations of CCND2 serve as a therapeutic target for precision medicine in lung cancer and breast cancer." (PMID 30308939, 2018). "The western cohort of The Cancer Genome Atlas also demonstrated CCND2 promoter hypermethylation in female lung cancer, lung adenocarcinoma, and breast cancer patients and that CCND2 promoter hypermethylation is an independent poor prognostic factor." (PMID 30308939, 2018). "We have described cyclin D2 to act as a negative regulator of the ETV4-induced responses in mammary cancer cells." (PMID 29996935, 2018). "Examples for hypermethylated breast cancer-associated genes are BRCA1, CCND2 (cyclin D2), ER, PR, CDH1 (E-cadherin), and many others." (PMID 29138528, 2017). "Although CCND2 over-expression is found in ovarian, testicular and gastric cancer, little is known about its role in breast cancer especially in the presence of lapatinib." (PMID 28288164, 2017). "The increased expression of Ccnd2 (cyclin D2) is discordant with enhanced tumorigenesis of early continuous HFD and HFD-LFD tumors, as loss of cyclin D2 expression is frequent in breast cancers and cyclin D2 has been considered to be a tumor suppressor." (PMID 26526858, 2015). "Examination of The Cancer Genome Atlas database revealed that Ccnd2 expression was altered (mainly amplified or upregulated) in 16 % of basal-like PAM50 breast cancers vs. altered (mainly downregulated) in 4 % of luminal A/B and 0 % in Her2+ breast cancers." (PMID 26526858, 2015). "When we applied the MS-HRM methods to biopsy samples of breast cancer patients, the promoters of CCND2, GSTP1, HIN-1 and RASSF1A were generally found to be methylated homogeneously." (PMID 26370119, 2015). "miR-503-5p was already emphasized in our previous work: this microRNA is highly expressed in endothelial cells and, can be secreted in exosomes and transferred into breast cancer cell lines to inhibit tumor growth by targeting CCND2 and CCND3." (PMID 26490435, 2015). "Recently, transcriptional silencing by aberrant methylation of promoter region of the CCND2 gene has been found in gastric cancer, breast cancer, prostate cancer, lung cancer, and Epstein–Barr virus-positive Burkitt's lymphoma." (PMID 24980822, 2014). "In breast cancer, where it has been studied most extensively, CCND2 hypermethylation is detected frequently, though it appears to be rarely detected in normal breast tissue." (PMID 21577262, 2011).
breast carcinoma (continued). "However, silencing of cyclin D2 expression by promoter methylation is also associated with cancer progression in breast cancer, lung, pancreatic and gastric cancer, suggesting that cyclin D2 might act as a tumor suppressor gene in a cancer-type dependent manner." (PMID 22303414, 2011). "Cyclin D2 is up regulated in many cancers, including breast cancer and its role is to increase cellular proliferation." (PMID 21529348, 2011). "Cyclin D2 (CCND2), which is often lost in breast cancer due to promoter hypermethylation, was significantly downregulated in LFS stromal cells, compared to WT (6.6 fold; p<0.012), suggesting a marked dysregulation of the cell cycle in these stromal cells." (PMID 21311097, 2010). "Expression of the CCND2 gene, which is located at chromosome 12p13, has been observed in various malignancies, including prostate cancer and breast cancer." (PMID 19239720, 2009). "Promoter hypermethylation of Cyclin D2, an important cell-cycle-regulatory gene that controls the transition from G1 to S phase, has been described in breast cancer." (PMID 17324252, 2007). "In breast cancer, repression of expression was attributed to methylation of the cyclin D2 gene promoter region." (PMID 15574200, 2004). "Recent studies suggested that cyclin D2 expression is inhibited by the aberrant methylation of the promoter region of the cyclin D2 gene in breast cancers as well as in Epstein–Barr virus-positive Burkitt's lymphoma." (PMID 12771922, 2003). "CCND2 is currently under investigation as a potential drug target for breast cancer treatment." (PMID 40009379, 2025). "In addition, upregulated CCND2, SNHG16, MYC, and GNAS levels were associated with accelerating cell cycle progression, as well as promoting growth and metastasis in lung cancer, breast cancer, and colon cancer." (PMID 37007962, 2023). "Although CCND2 dysregulation is a significant source of medication resistance in breast cancer endocrine treatment, its significance in LUAD remains unknown." (PMID 36816016, 2023). "CCND2 upregulated and could be a therapeutic target for a variety of tumors, including colon cancer, stomach cancer, liver cancer, breast cancer and lung cancer as well as ovarian cancer." (PMID 35306579, 2022). "However, some genes in previous studies are inconsistent with our study; for instance, upregulated lncRNA GACAT3 in breast cancer enhances its endogenous target CCND2 through sponging miR-497, which was found to be correlated with a poor prognosis." (PMID 35846145, 2022). "CCND2 upregulated and could be a therapeutic target for a variety of tumors, including colon cancer, stomach cancer, liver cancer, breast cancer and lung cancer, etc.." (PMID 35306579, 2022). "There are also studies conducted on promoter methylation states of 100 genes, including BRCA1, CCND2, BCL2, MDR1, IL10, and TWIST, recorded to understand how alteration between hypermethylation and hypomethylation over time contributes to select breast cancer susceptibility biomarkers." (PMID 34576196, 2021). "Both miR-15 and miR-16 are considered as tumor suppressors that could be used for therapy of inhibiting BCL2-, CCND1-, and CCND2-overexpressing tumors, e.g., chronic lymphocytic leukemia, breast cancer, prostate, and lung cancer." (PMID 33788050, 2021). "Furthermore, our IHC staining of breast carcinoma tissues demonstrated a reciprocal profile of FBXL8 versus CCND2 and IRF5 with cancer advancement over stages I–III." (PMID 32784654, 2020). "Reduced expression of cyclin D2 was observed in breast cancer, non‐small cell lung cancer, pancreatic cancer and prostate cancer, indicating that cyclin D2 may act as a tumour suppressor in these cancers." (PMID 32893977, 2020). "However, hypermethylation of the CCND2 gene is common in many cancers, including lung and breast cancer, and it results in low CCND2 expression." (PMID 30308939, 2018).
breast carcinoma (continued). "In our previous study, we observed that antroquinonol D could decrease methylation and induce CCND2 expression in breast cancer MDA-MB-231 cells." (PMID 30308939, 2018). "In addition, CCND2 promoter hypermethylation was detected in plasma circulating cell-free DNA from 8 of 18 (44.4%) of breast cancer patients, and little CCND2 promoter hypermethylation was detected in women without breast cancer (3 of 19, 15.8%)." (PMID 30308939, 2018). "In this study, we found that low CCND2 expression was associated with a poor prognosis, especially in patients with non-small cell lung cancer (NSCLC) or breast cancer; thus, CCND2 might serve as a potential drug target." (PMID 30308939, 2018). "To verify whether CCND2 showed promoter hypermethylation in Taiwanese breast cancer patients, we performed qMSP to analyze the methylation levels in 93 tumors and paired adjacent normal tissues of breast cancer patients." (PMID 30308939, 2018). "Adjusted for sex, race, age, tumor type, and stage, the multivariate Cox proportional hazard model analysis showed a significant correlation of CCND2 expression with the five-year overall survival in lung cancer and 10-year overall survival in breast cancer (p = 0.021 and 0.001, respectively)." (PMID 30308939, 2018). "We found 38 of 93 (40.9%) of breast cancer patients showed CCND2 promoter hypermethylation." (PMID 30308939, 2018). "Furthermore, the CCND2 promoter and exon 1 regions exhibited significantly increased methylation levels in breast tumors compared with paired adjacent normal tissues of breast cancer in TCGA." (PMID 30308939, 2018). "We found that CCND2 is a common target in lung and breast cancer." (PMID 30308939, 2018). "However, promoter hypermethylation of CCND2 is frequent in several solid cancers, such as breast cancer, lung cancer, and liver cancer." (PMID 30308939, 2018). "However, breast cancer and lung adenocarcinoma showed a higher frequency of low CCND2 mRNA expression than adjacent normal tissues." (PMID 30308939, 2018). "Hypermethylation of CCND2 could be successfully detected in the plasma of breast cancer patients compared with that in healthy persons." (PMID 30308939, 2018). "CCND2 is a potential target for lung and breast cancer in future personalized medicine." (PMID 30308939, 2018). "Future studies should verify whether antroquinonol or antroquinonol D could be a potential drug for lung cancer or breast cancer patients with hypermethylation of CCND2 or CCND2 low expression and improve the survival rate in these patients." (PMID 30308939, 2018). "Likewise, it was reported that majority of primary breast carcinomas lack expression of CCND2 mRNA (18 of 24) and protein (10 of 13)." (PMID 27583477, 2016). "It is noteworthy that Ccnd2 expression may be specifically elevated in poorly differentiated breast cancer cells that exhibit features of epithelial-mesenchymal transition and a higher potential for metastasis." (PMID 26526858, 2015). "In breast cancer, several critical genes reportedly undergo aberrant hypermethylation, including genes involved in cell cycle regulation (p16, Cyclin D2), cell apoptosis (DAPK), DNA repair (BRCA1), cell adhesion (CDH1) and cell signal transduction (ER and RARβ2)." (PMID 26451736, 2015). "PIAS1 acts by delineating histone modifications and DNA methylation to silence the expression of a subset of clinically relevant genes, including breast cancer DNA methylation signature genes such as cyclin D2 and estrogen receptor, and breast tumor suppressor WNT5A." (PMID 24586797, 2014). "In contrast, reduction or lack of CCND2 expression has also been reported in gastric cancer, breast cancer, prostate cancer, and lung cancer, suggesting that CCND2 may function as a TSG." (PMID 24980822, 2014).